TMEM86B (transmembrane protein 86B)
Description:
Catalyzes the hydrolysis of the vinyl ether bond of choline or ethanolamine lysoplasmalogens, forming fatty aldehyde and glycerophosphocholine or glycerophosphoethanolamine, respectively and is specific for the sn-2-deacylated (lyso) form of plasmalogen.
Synonyms: MGC30208
Tractability: Antibody: UniProt predicts a signal peptide or a membrane-spanning region.
Gene: Protein-coding gene on chromosome 19 (55,226,638 to 55,228,784, reverse strand). Ensembl gene ENSG00000180089.
Subcellular location: Endoplasmic reticulum membrane; Cytoplasm
Subcellular location (Human Protein Atlas): Centrosome; Midbody
Pathways (Reactome):
Metabolism: Acyl chain remodelling of PC
Gene Ontology:
Molecular function: alkenylglycerophosphocholine hydrolase activity; D-lysine 5,6-aminomutase activity; identical protein binding; protein binding; ether hydrolase activity
Biological process: ether lipid metabolic process; phosphatidylcholine acyl-chain remodeling
Cellular component: cytoplasm; membrane; endoplasmic reticulum membrane
Genetic constraint (gnomAD): Loss-of-function variants: 15 observed, 12.01 expected, observed/expected ratio (o/e) 1.25, 90% interval 0.83 to 1.82. The synonymous counts are far from expectation, so gnomAD's model fits this gene poorly and the ratio says little. Missense variants: 328 observed, 279.31 expected, observed/expected ratio (o/e) 1.17, 90% interval 1.07 to 1.29. Synonymous variants: 173 observed, 131.57 expected, observed/expected ratio (o/e) 1.31, 90% interval 1.16 to 1.49.
Homologues: Orthologues: chimpanzee TMEM86B (98% identical), rat Tmem86b (69% identical), mouse Tmem86b (66% identical), guinea pig TMEM86B (65% identical), dog TMEM86B (63% identical), rabbit TMEM86B (62% identical), zebrafish tmem86b (31% identical), Drosophila melanogaster CG7582 (31% identical). Paralogues in human: TMEM86A (36% identical).
Diseases named in the same sentence as TMEM86B in open-access papers:
TMEM86B is named in the same sentence as 4 diseases in open-access papers, as found by Europe PMC text mining. Sharing a sentence is not in itself a finding about the gene and the disease. The quoted sentences say what the papers report.
colon cancer (1 paper, 2025). "To evaluate the clinical significance of TMEM86B in colorectal cancer, we analyzed data from the GEPIA2 database, which showed that elevated TMEM86B expression was significantly associated with poorer prognosis in colon cancer patients." (PMID 40697926, 2025).
colorectal cancer (1 paper, 2025). A primary or metastatic malignant neoplasm that affects the colon or rectum. "Considering the limited functional characterization of TMEM86B in colorectal cancer to date, it represents a promising candidate for uncovering novel oncogenic mechanisms." (PMID 40697926, 2025). "Core mitochondrial metabolism-related gene, TMEM86B promotes colorectal cancer progression by enhancing cell proliferation, migration, and invasion, and its downregulation significantly inhibits tumor growth both in vitro and in vivo." (PMID 40697926, 2025). "In this study, we examined its potential role in colorectal cancer progression and provided robust evidence that TMEM86B facilitates malignant phenotypes, underscoring its contribution to tumor development." (PMID 40697926, 2025). "TMEM86B promotes colorectal cancer progression, and its downregulation inhibits tumor growth in vitro and in vivo." (PMID 40697926, 2025). "In addition, TMEM86B was identified as a key gene promoting colorectal cancer progression, suggesting its potential as a therapeutic target." (PMID 40697926, 2025). "In our previous analysis, multifactorial Cox regression identified TMEM86B, TNFAIP8L3, and HDC as independent prognostic factors for colorectal cancer (CRC) (p < 0.05) among the 15 mitochondrial metabolism-related genes." (PMID 40697926, 2025).
tumor (1 paper, 2025). "TMEM86B expression was significantly higher in tumor tissues (p < 0.05), whereas TNFAIP8L3 and HDC levels were significantly lower in tumors compared to normal tissues (p < 0.05)." (PMID 40697926, 2025). "Tumor samples exhibited higher expressions of TMEM86B, lower expressions of HDC and TNFAIP8L3 compared to normal tissues." (PMID 40697926, 2025). "TMEM86B was identified as a potential oncogene, and its knockdown inhibited tumor growth in vitro and in vivo." (PMID 40697926, 2025). "Moreover, TMEM86B was consistently upregulated in tumor tissues compared to normal controls across multiple datasets." (PMID 40697926, 2025). "In addition to the in vitro findings, we examined the impact of TMEM86B knockdown on tumor growth in vivo." (PMID 40697926, 2025). "Both the average tumor volume and weight were significantly decreased in the TMEM86B knockdown groups compared to their respective controls (RKO/shNC vs. RKO/shTMEM86B; HCT116/shNC vs. HCT116/shTMEM86B), indicating that TMEM86B down-regulation suppresses tumor growth in vivo." (PMID 40697926, 2025). "Given its predicted mitochondrial membrane localization and involvement in lipid metabolism, TMEM86B may play a role in mitochondrial lipid remodeling, membrane integrity, or metabolic reprogramming—processes that are critical for tumor development and invasion." (PMID 40697926, 2025). "The nomogram, which incorporates independent prognostic genes TMEM86B, TNFAIP8L3, HDC, and key clinical features pTNM stage (pathological Tumor-Node-Metastasis), age, was created to predict patient outcomes." (PMID 40697926, 2025).
TMEM86B also shares sentences with these, for which no sentence is quoted: severe acute respiratory syndrome coronavirus 2 (1 paper).